ENOX2 (ecto-NOX disulfide-thiol exchanger 2)
Description:
May be involved in cell growth. Probably acts as a terminal oxidase of plasma electron transport from cytosolic NAD(P)H via hydroquinones to acceptors at the cell surface. Hydroquinone oxidase activity alternates with a protein disulfide-thiol interchange/oxidoreductase activity which may control physical membrane displacements associated with vesicle budding or cell enlargement. The activities oscillate with a period length of 22 minutes and play a role in control of the ultradian cellular biological clock.
Synonyms: tNOX; COVA1; APK1
Tractability: Antibody: UniProt places it where antibodies can reach, with medium confidence; its Gene Ontology location is reachable by antibodies, with medium confidence. PROTAC: ubiquitination databases record sites on it.
Target class: Transporter
Gene: Protein-coding gene on chromosome X (130,622,325 to 130,903,272, reverse strand). Ensembl gene ENSG00000165675.
Subcellular location: Cell membrane; Secreted, extracellular space
Subcellular location (Human Protein Atlas): Cytosol; Plasma membrane
Gene Ontology:
Molecular function: nucleic acid binding; RNA binding
Biological process: electron transport chain; ultradian rhythm
Cellular component: external side of plasma membrane; plasma membrane; cytosol; extracellular region
Homologues: Orthologues: chimpanzee ENOX2 (99% identical), macaque ENOX2 (99% identical), rabbit ENOX2 (99% identical), dog ENOX2 (98% identical), rat Enox2 (95% identical), mouse Enox2 (94% identical), pig ENOX2 (92% identical), guinea pig ENOX2 (92% identical), Drosophila melanogaster CG10948 (41% identical). Paralogues in human: ENOX1 (69% identical).
Diseases named in the same sentence as ENOX2 in open-access papers:
ENOX2 is named in the same sentence as 34 diseases in open-access papers, as found by Europe PMC text mining. Sharing a sentence is not in itself a finding about the gene and the disease. The quoted sentences say what the papers report.
melanoma (6 papers, 2014 to 2024). A malignant, usually aggressive tumor composed of atypical, neoplastic melanocytes. "We discovered that high ENOX2 expression in primary melanoma (PM) was associated with decreased overall (OS), disease-specific (DSS) and metastasis-free survival (MFS), suggesting suitability as a complementary biomarker." (PMID 39519404, 2024). "In this study, we evaluated the role of ecto-NOX disulfide-thiol exchanger 2 (ENOX2/tNOX), a cancer- and growth-associated protein, in the prognosis and therapy of primary malignant melanoma." (PMID 39519404, 2024). "Sera of patients with malignant melanoma contained an ENOX2 transcript variant of 37 to 41 kDa, pH 4.6 to 5.3." (PMID 24393573, 2014). "High levels of ENOX2 protein were associated with a significantly increased incidence of metastases, both when considering all PMs (pGBW = 0.0191; pLR = 0.0182) and stage I and II melanomas (pGBW = 0.0015; pLR = 0.0019)." (PMID 39519404, 2024). "Similarly, the detection of a melanoma-specific ENOX2 variant with a molecular weight between 37 kDa and 41 kDa was not possible." (PMID 39519404, 2024). "This work focuses on the role of ENOX2 as a potential prognostic marker and in the treatment of malignant melanoma." (PMID 39519404, 2024). "A gradual rise in ENOX2 expression was found with an increase in malignant potential from benign nevi (BNs) via PMs to melanoma metastases (MMs), as well as with an increasing tumor thickness and stage." (PMID 39519404, 2024). "It is possible that an increased number of eTILs as part of an antitumor immune response can also be generated in melanoma through treatment with ENOX2 inhibitors." (PMID 39519404, 2024). "This study focused on the role of ENOX2 as a target for the prognosis and therapy of malignant melanoma." (PMID 39519404, 2024). "We discovered that high ENOX2 expression is associated with decreased overall (OS), disease-specific (DSS) and metastasis-free survival (MFS) in primary melanoma (PM) and a reduction in electronic tumor-infiltrating lymphocytes (eTILs)." (PMID 39519404, 2024). "There are even studies on tumor-specific ENOX2 isoforms; for example, specific ENOX2 isoforms with molecular weights between 37 and 41 kDa were found in the sera of melanoma patients." (PMID 39519404, 2024). "Only in the 72 kDa range were ENOX2 bands consistently detected in all melanoma and benign cell lines." (PMID 39519404, 2024). "The expression of ENOX2 mRNA and protein in melanoma provided a potential prognostic marker." (PMID 39519404, 2024). "In conclusion, ENOX2 may serve as a potential prognostic marker and therapeutic target in malignant melanoma." (PMID 39519404, 2024). "However, high ENOX2 expression could still be used as a dependent prognostic biomarker to identify particularly aggressive melanomas." (PMID 39519404, 2024).
lung carcinoma (4 papers, 2016 to 2023). "To detect ENOX2 protein, here we developed an E-DNA biosensor that changed conformation upon ENOX2 binding, resulting in a detectable current signal decrease (a “signal-off” response) enabling sensitive and specific detection of ENOX2, a diagnostic biomarker of lung cancer and other cancer types." (PMID 37504074, 2023). "Those cancers exhibit a single ENOX2 protein unique to lung cancer but can be distinguished by their pIs." (PMID 26807072, 2016).
cervical carcinoma (3 papers, 2014 to 2020). A carcinoma arising from either the exocervical squamous epithelium or the endocervical glandular epithelium. "Sera from cervical cancer patients contained a 90-100 kDa ENOX2 transcript variant, pH 4.2-5.4." (PMID 24393573, 2014).
oral cancer (3 papers, 2022 to 2026). "In xenograft models, ENOX2-overexpressing oral cancer cell spheroids exhibited enhanced tumorigenicity, while ENOX2-silenced spheroids formed significantly smaller tumors." (PMID 41596158, 2026). "In this study, we investigated the potential role of ENOX2 in regulating stemness properties in oral cancer through a combination of in vitro, in vivo, and bioinformatics approaches." (PMID 41596158, 2026). "Collectively, our results identify ENOX2 as a potential regulator of oral cancer stemness and provide a conceptual foundation for future studies aimed at elucidating its downstream pathways and clinical relevance in head and neck tumors." (PMID 41596158, 2026).
colorectal cancer (2 papers, 2014 to 2019). A primary or metastatic malignant neoplasm that affects the colon or rectum. "Sera of colorectal cancer patients contained at least two of three possible ENOX2 transcript variants of 80 to 96 kDa, pH 4.5 to 5.3, or 50 to 60 kDa, pH 4.2 to 5.1 or 33 to 46 kDa, pH 3.8-5.2." (PMID 24393573, 2014).
mesothelioma (2 papers, 2014 to 2016). A usually malignant and aggressive neoplasm of the mesothelium which is often associated with exposure to asbestos. "Two mesothelioma-specific ENOX2 protein transcript variants were detected in the serum of asbestos-exposed individuals 4–10 years prior to clinical diagnosis of malignant mesothelioma (average 6.2 years)." (PMID 26807072, 2016). "Overall, both of the mesothelioma-specific ENOX2 transcript variants were detected 4–10 years in advance of clinical symptoms and with an average of 6.2 ± 2.6 years in advance of clinical symptoms." (PMID 26807072, 2016). "In this study, serum presence of mesothelioma-specific protein transcript variants of ecto-nicotinamide adenine dinucleotide oxidase disulfide-thiol exchanger 2 (ENOX2), a recently identified marker of malignancy, were investigated using the ONCOblot tissue of origin cancer detection test." (PMID 26807072, 2016). "The presence of one of the mesothelioma-associated ENOX2 transcript variants may reflect this interaction." (PMID 26807072, 2016). "Sequential serum samples collected from asbestos-exposed individuals prior to the development of frank mesothelioma were assayed for ENOX2 presence by 2-D gel immunoblot analysis to determine how long in advance of clinical symptoms mesothelioma-specific ENOX2 transcript variants could be detected." (PMID 26807072, 2016). "All 17 patients who were diagnosed with malignant mesothelioma displayed both mesothelioma-specific protein ENOX2 isoforms." (PMID 26807072, 2016). "The largest spot diameter encountered in patients clinically diagnosed with mesothelioma was 6.6 mm representing a nearly tenfold increase in ENOX2 proteins in the serum compared to levels giving rise to a 2 mm diameter spot at early detection." (PMID 26807072, 2016). "This represented approximately a twofold increase in serum ENOX2 concentration between the initial date of early detection and the clinical diagnosis of frank mesothelioma." (PMID 26807072, 2016). "The two ENOX2 transcripts were apparent in the seven mesothelioma patients examined, 4–11 years before the clinical onset of disease." (PMID 26807072, 2016). "Only one subject (ID 1268), was positive for both mesothelioma specific ENOX2 protein transcripts." (PMID 26807072, 2016). "In contrast, the amount of ENOX2 detected in the sera of time series subjects who have not developed mesothelioma either remained constant or declined." (PMID 26807072, 2016).
asbestosis (1 paper, 2016). A lung disorder caused by inhalation of asbestos fibers. "Either one or both ENOX2 protein transcript variants indicative of malignant mesothelioma were absent in 14 of 15 subjects diagnosed with benign pleural plaques either with or without accompanying asbestosis." (PMID 26807072, 2016).
leukemia (1 paper, 2014). A malignant (clonal) hematologic disorder, involving hematopoietic stem cells and characterized by the presence of primitive or atypical myeloid or lymphoid cells in the bone marrow and the blood. "A 38 to 48 kDa ENOX2 transcript variant of low isoelectric point pH 3.6 to 4.5 was characteristic of leukemias, lymphomas and other blood cell cancers." (PMID 24393573, 2014).
malignant mesothelioma (1 paper, 2016). A malignant neoplasm of the pleura or peritoneum, arising from mesothelial cells. "In a population of asbestos-exposed subjects who eventually developed malignant mesothelioma, ENOX2 protein transcript variants characteristic of malignant mesothelioma were present in serum 4–10 years in advance of clinical symptoms." (PMID 26807072, 2016). "In a population of asbestos-exposed subjects who eventually developed malignant mesothelioma, ENOX2 transcript variants characteristic of malignant mesothelioma were present in serum 4–10 years in advance of clinical symptoms." (PMID 26807072, 2016). "For malignant mesothelioma two ENOX2 protein transcript variants are evident; indeed multiple ENOX2 isoforms are seen in approximately half of the different types of cancer." (PMID 26807072, 2016). "The signature pattern of ENOX2 isoforms produced by malignant mesothelioma consisted of two ENOX2 transcript variants." (PMID 26807072, 2016). "This examination of serum samples from asbestos-exposed subjects revealed that patients with a clinically confirmed diagnosis of malignant mesothelioma produced a consistent pattern of two ENOX2 transcript variants." (PMID 26807072, 2016). "Therefore, the present study was undertaken to determine if cancer-specific ENOX2 transcript variants might serve as biomarkers to detect the presence of malignant mesothelioma in advance of clinical symptoms." (PMID 26807072, 2016). "Consistently, two isoforms of ENOX2 were detected in sera samples collected from subjects an average 7.5 months (SD = 8) after confirmed diagnosis of malignant mesothelioma." (PMID 26807072, 2016). "Malignant mesothelioma is characterized by the presence of two ENOX2 protein species of molecular weight 64 and 41 kDa, and pI 3.9 and 4.3, respectively." (PMID 26807072, 2016). "Importantly, both ENOX2 isoforms were required for a correct identification of malignant mesothelioma by using the ONCOblot test." (PMID 26807072, 2016). "The data from this study demonstrate that serum ENOX2 proteins characteristic of malignant mesothelioma can be detected in subjects 4–11 years before diagnosis based on clinical symptoms, and raises the possibility that the benefits of early intervention could be studied in such individuals." (PMID 26807072, 2016).
nasopharyngeal carcinoma (1 paper, 2024). A carcinoma arising from the nasopharyngeal epithelium. "In nasopharyngeal carcinoma, high ENOX2 expression is associated with lower immune infiltration and poorer progression-free survival." (PMID 39519404, 2024). "This could also explain the increase in immune infiltration due to ENOX2 inhibition with PXD in nasopharyngeal carcinoma." (PMID 39519404, 2024).
non-small cell lung carcinoma (1 paper, 2014). A group of at least three distinct histological types of lung cancer, including non-small cell squamous cell carcinoma, adenocarcinoma, and large cell carcinoma. "Sera from patients with non-small cell lung carcinoma contained a 53 to 56 kDa ENOX2 transcript variant, pH 4.7-5.3 while sera from ovarian cancer patients contained two ENOX2 transcript variants of 72 to 90 kDa and 37 to 47 kDa, both pH 3.7 to 5.0." (PMID 24393573, 2014). "Interestingly, among the ENOX2 transcript variants with the greatest incidence, 16 and 20%, were those characteristic of breast and non-small cell lung cancer, two cancers generally regarded as characterized by extended latency periods perhaps even as long as 20 years." (PMID 24393573, 2014).
osteonecrosis (1 paper, 2021). A none disease characterized by death of bone tissue due to a lack of blood supply. "In the Steroid-induced osteonecrosis of the femoral head-bone marrow mesenchymal stem cells, five circRNA targeted mRNAs including CLASP1, ENOX2, SYK, UBE2G2, and WNT5B were up-regulated by circRNA42." (PMID 34753940, 2021).
prostate carcinoma (1 paper, 2014). A carcinoma that arises from epithelial cells of the prostate gland. "Sera from patients with prostate cancer contained 71 to 88 kDa ENOX2 transcript variants of isoelectric point, pH 5.1-6.5." (PMID 24393573, 2014).
cancer (25 papers, 2005 to 2026). A tumor composed of atypical neoplastic, often pleomorphic cells that invade other tissues. "The ENOX2 protein has an influence on the infiltration of immune cells into cancer tissue, with high ENOX2 expression being associated with lower immune infiltration." (PMID 39519404, 2024). "Idronoxil has been described as a potent inhibitor of a cancer associated splice variant of ENOX2 – tNOX, oncofetal protein, which is re-expressed by cancer cells upon transformation." (PMID 36936272, 2022). "Cancer cells also express on their surface a unique tumor-associated hydroquinone (NADH) oxidase with protein disulfide–thiol exchange activity (tNOX/ENOX2), which contributes to the generation of ROS (mainly superoxide) and induction of oxidative stress." (PMID 35158753, 2022). "We previously demonstrated that capsaicin preferentially inhibits a tumor-associated NADH oxidase (tNOX, ENOX2) in cancer/transformed cells, and, thereby, enhances ROS generation and apoptosis." (PMID 31635402, 2019). "At least 20 tissue of origin specific patterns of ENOX2 transcript variants have been described (and/or combinations of isoforms) indicative of the cancer tissue of origin." (PMID 26807072, 2016). "ENOX2 transcript variants of specific molecular weights and isoelectric points (pIs) are produced uniquely by patients with cancer." (PMID 26807072, 2016). "One hundred ten subjects were tested for cancer presence using the ONCOblot® Tissue of Origin 2-D gel/western blot protocol for detection of serum presence of transcript variants of the ENOX2 protein." (PMID 24393573, 2014). "The cancer-specific ENOX2 transcript variants result from cancer-specific expression of alternatively spliced mRNAs." (PMID 24393573, 2014). "Analyses using this antibody, when combined with two-dimensional gel electrophoretic separation, revealed specific ENOX2 species subsequently identified as transcript variants, each with a characteristic molecular weight and isoelectric point indicative of a particular form of cancer." (PMID 24393573, 2014). "Human tumor-associated NADH oxidase (ENOX2, also known as tNOX) is a cancer cell-specialized NADH oxidase that is expressed on the membranes of cancer cells." (PMID 41596158, 2026). "A promising early detection biomarker is Ecto-NOX disulfide–thiol exchanger 2 (ENOX2, also referred to as tNOX), which is detectable in the blood prior to observable clinical cancer symptoms." (PMID 37504074, 2023). "An attractive cancer target for diagnostic blood tests is human Ecto-NOX disulfide–thiol exchanger 2 (ENOX2), expressed in most human cancer types and regularly shed into blood sera." (PMID 37504074, 2023). "We previously identified a tumor-associated NADH oxidase (tNOX, ENOX2) that oxidizes NADH or hydroquinones to the oxidized NAD+ form, and demonstrated that it is involved in regulating cancer cell growth." (PMID 28122359, 2017). "The identification of specific ENOX2 isoforms in sera can be indicative of the presence of cancer and also indicative of the cancer site." (PMID 26807072, 2016). "The predictive correlation between ONCOblot findings and the onset of cancer is based on findings that support ENOX2 as a marker of cancer presence." (PMID 26807072, 2016). "These ENOX2 proteins are shed into the circulation and can be detected in some early stage cancers, including: breast, lung, colon, prostate and ovarian cancer." (PMID 26807072, 2016). "The approach to early intervention is based on previous work in cell culture models showing that ENOX2 proteins are required to support the unregulated growth that typifies cancer cells." (PMID 24393573, 2014). "If the growth function of ENOX2 is blocked for 48 to 72 h, the cancer cells cannot enlarge following division, cannot pass the checkpoint in G1 that monitors cell size and eventually undergo programmed cell death (apoptosis)." (PMID 24393573, 2014).